RN7SL589P (RNA, 7SL, cytoplasmic 589, pseudogene)
Gene: Miscellaneous RNA gene on chromosome 4 (2,316,197 to 2,316,506, reverse strand). Ensembl gene ENSG00000239247.
Homologues: Orthologues: chimpanzee Metazoa_SRP (99% identical), macaque Metazoa_SRP (88% identical). Paralogues in human: RN7SL1 (80% identical), RN7SL2 (80% identical), RN7SL3 (79% identical), RN7SL797P (79% identical), RN7SL126P (79% identical), RN7SL321P (78% identical), RN7SL431P (77% identical), RN7SL441P (77% identical), RN7SL735P (77% identical), Metazoa_SRP (77% identical), RN7SL45P (77% identical), RN7SL130P (77% identical), and 698 more.